IL6 (interleukin 6)
Diseases named in the same sentence as IL6 in open-access papers (continued):
Sharing a sentence is not in itself a finding about the gene and the disease.
rheumatoid arthritis (continued). "In particular, MMP‐9 and IL‐6 may be the best targets for prospective studies since they have been closely linked to the pathogenesis of chronic obstructive pulmonary disease, emphysema, rheumatoid arthritis, and various cancers." (PMID 38353387, 2024). "TCZ, an IL-6R antibody (Ab) that globally blocks IL-6 activities through IL-6R-α and sIL-6R, is associated with a significant reduction in the QTc interval in patients with rheumatoid arthritis (RA)." (PMID 39125976, 2024). "In a rheumatoid arthritis (RA) mouse model, GPR65 deficiency reduced hyperalgesia and RA score and significantly decreased IL-6 and IL-17 production." (PMID 39336742, 2024). "Furthermore, cytokines including TNF-α, IL-6, and IL-1 can cause fibroblasts and other cells to release MMPs and activate NF-κB, both of which contribute to the degeneration of bone and cartilage tissue in rheumatoid arthritis." (PMID 39766566, 2024). "Furthermore, IL-6 is also implicated in the pathogenesis of rheumatoid arthritis." (PMID 37829623, 2023). "Although CRP could reflect the inflammatory status of the whole body, when a patient is combined with other chronic inflammatory diseases, such as rheumatoid arthritis, some cytokines such as interleukin 6 can act directly on muscle tissue, causing a decrease in muscle strength and mass." (PMID 37488531, 2023). "In inflammatory diseases such as rheumatoid arthritis (RA), elevated IL-6 levels are allied with decreased HDL-C and HDL-associated protein apoA-1." (PMID 37627620, 2023). "NF-κB activation can also promote the expression of interleukin-6 (IL-6), which is a pro-inflammatory cytokine known to promote osteoclastogenesis and inhibit osteoblastogenesis and is therefore commonly associated with various bone diseases such as rheumatoid arthritis and osteoporosis." (PMID 36743421, 2023). "The underlying cause remains to be fully understood, but higher IL-6 levels in the urine of patients with rheumatoid arthritis have been considered to originate from subclinical renal injury and/or may be related to serum IL-6 levels, which are increased in these patients." (PMID 37189804, 2023). "Most studies that focus on immune diseases, such as rheumatoid arthritis, psoriasis or multiple sclerosis, and the key factors related to pathogenic differentiation of Th17 and Th22 cells and the production of IL-17 and IL-22 in their course, emphasize the pro-inflammatory importance of IL-6." (PMID 35407663, 2022). "The IL-6 (with IL-6 being downstream IL-1) antagonist, tocilizumab, which blocks soluble and membrane‐bound IL‐6R, exerts beneficial effects in a high‐risk population (rheumatoid arthritis patients), even as it increases total cholesterol and low‐density lipoprotein levels." (PMID 36466820, 2022). "Various conditions, such as denervation, disuse, aging, rheumatoid arthritis (RA), Crohn’s disease, and cachexia, can cause muscle atrophy, which are all characterized by elevated levels of circulating pro-inflammatory mediators in patients, such as TNFα, IL-1β, and/or IL-6." (PMID 36618945, 2022). "For instance, a meta-analysis of European and Asian studies on IL-6 SNP and rheumatoid arthritis (RA) risk showed that IL-6 SNP was significantly associated with RA in Asian patients but not in the Caucasian population." (PMID 34327025, 2021). "Therefore, it is recognized that IL-6 is a promoter of osteoclastic bone resorption and centrally involved in the pathogenesis of bone loss in chronic and acute inflammation, periodontitis, rheumatoid arthritis, and osteoporosis." (PMID 32708317, 2020). "IL-6 trans-signalling has also been implicated in other diseases such as chronic inflammatory bowel disease and colon cancer, with a humanized monoclonal IL-6R antibody (tocilizumab) currently licensed for use in rheumatoid arthritis and systemic juvenile idiopathic arthritis." (PMID 31395050, 2019).
rheumatoid arthritis (continued). "Due to this crucial role in inflammation, dysregulated IL-6-induced signalling is associated with the development of severe immunological and proliferative diseases such as rheumatoid arthritis (RA), inflammatory bowel disease (IBD), and colon cancer." (PMID 31101051, 2019). "The objectives of this study were to determine the periodontal and salivary variables most related to the risk of RA, and even examine wether interleukin-6 (IL-6) levels are elevated in patients with rheumatoid arthritis versus a control group." (PMID 28809379, 2017). "Over-production of IL-6 is a hallmark of immune-mediated inflammatory diseases such as Castleman’s Disease (CD) and rheumatoid arthritis (RA)." (PMID 26555695, 2015). "On the other hand, enhanced IL-6 responses accounted for the enhanced susceptibility of Socs3fl/flvav cre or Socs3fl/flLysM cre (deficient in SOCS3 in myeloid cells) mice to induced inflammatory diseases like rheumatoid arthritis (RA) or experimental autoimmune encephalomyelitis (EAE)." (PMID 24600449, 2014). "Subsequent studies have shown that dysregulation of IL-6 production is implicated in the pathogenesis of Castleman's disease, rheumatoid arthritis (RA), and various other autoimmune, inflammatory, and malignant diseases." (PMID 22315615, 2012). "Integrating these data suggests that GABA may play a role in downregulating mechanisms that lead to the production of proinflammatory agents such as interleukin-1, interleukin-6, and matrix metalloproteinase 3 – agents implicated in the pathogenesis of rheumatoid arthritis (RA)." (PMID 18171484, 2008). "Interleukin-6 is a key pro-inflammatory cytokine that plays a central role in the pathogenesis of rheumatoid arthritis by activating downstream inflammatory signaling pathways." (PMID 41797973, 2026). "The activation of IL-6 signal plays a major role in the pathogenesis of AQP4+ NMOSD as well as rheumatoid arthritis (RA)." (PMID 41596603, 2026). "Rheumatoid arthritis (RA) is a chronic autoimmune disorder characterized by joint inflammation and destruction, with interleukin-6 (IL-6) playing a central role in its pathogenesis by driving inflammatory responses." (PMID 41797973, 2026). "Clinically, the relevance of this pathway is underscored by evidence that IL-6 blockade with tocilizumab lowers bone resorption and preserves bone mineral density in inflammatory conditions such as rheumatoid arthritis." (PMID 41562931, 2026). "Tocilizumab, a humanized monoclonal antibody targeting interleukin-6 (IL-6) signaling, is widely used to treat rheumatoid arthritis and other autoimmune conditions." (PMID 41333011, 2025). "Overshooting activities of IL-6 and other cytokines are found in all inflammatory diseases, making them attractive therapeutic targets for the treatment of patients with rheumatoid arthritis or inflammatory bowel disease." (PMID 40663802, 2025). "IL-6 plays a major role in rheumatoid arthritis by mediating the inflammatory response, exacerbating joint damage and promoting the autoimmune response." (PMID 40666523, 2025). "In rheumatoid arthritis, synoviocytes and macrophages maintain a chronic pro-inflammatory profile, sustained by IL-6 and TNF-α, inhibiting repair and promoting joint destruction." (PMID 41373540, 2025). "■Inhibition of CD4+ and CD8+ T cell proliferation and IFN-γ, TNF-α, IL-6, and IL-17 release in rheumatoid arthritis;■Reduced iNOS expression induced by LPS in murine macrophages." (PMID 40298549, 2025). "Specifically, the efficacy of this bacterial delivery should be evaluated in chronic inflammatory diseases such as rheumatoid arthritis, which are correlated with failure of IL-6 control." (PMID 41003755, 2025). "Serum and synovial fluid levels of IL-6 are increased in rheumatoid arthritis (RA), where it plays a role in pannus development, synovial angiogenesis, and joint destruction." (PMID 41127878, 2025).
rheumatoid arthritis (continued). "Targeting cytokines such as TNF-α and IL-6 has been effective in reducing inflammation in autoimmune disorders like rheumatoid arthritis." (PMID 40364844, 2025). "Inhibitors of the IL-6/IL-6R system have been approved by the FDA for rheumatoid arthritis and Castleman’s disease: Tocilizumab (Actemra) and Sarilumab (Kevzara) target the membrane and soluble IL-6 receptors, Siltuximab (Sylvant) targets IL-6." (PMID 40610814, 2025). "In synovial inflammatory conditions such as rheumatoid arthritis, activated synovial macrophages and synovial fibroblasts secrete proinflammatory cytokines such as IL-1, IL-6, and TNF-α." (PMID 40128226, 2025). "The patient’s serum IL-6 level was increased after tocilizumab administration, as it is in rheumatoid arthritis and Castleman’s disease." (PMID 40255422, 2025). "Tocilizumab, another IL-6 inhibitor, has been explored in inflammatory conditions such as rheumatoid arthritis and has shown potential in reducing systemic inflammation." (PMID 40002874, 2025). "IL-6 inhibitors, such as tocilizumab, have been shown to inhibit hepcidin proliferation and improve anemia in inflammatory autoimmune diseases including rheumatoid arthritis and Castleman disease." (PMID 41204476, 2025). "In the joints, synovial fibroblasts utilize EEF1A1 to accelerate the translation of IL-6 and IL-8, establishing a positive feedback loop of “translation-inflammation coupling” that promotes the progression of rheumatoid arthritis." (PMID 41262540, 2025). "In an in vitro co-culture model using rheumatoid arthritis synovial fibroblasts and human umbilical vein endothelial cells, IL-6 stimulation increased VEGF expression and decreased Ang-1 expression, whereas VEGF stimulation alone did not alter Ang-1 levels." (PMID 41010841, 2025). "Conversely, in rheumatoid arthritis, macrophages exacerbate inflammation and tissue damage by releasing pro-inflammatory cytokines such as IL-6 and TNF-α." (PMID 40055311, 2025). "Elevated levels of IL-6, IL-18, IFNγ, IL-17, IL-23, and TNFα have been found in the serum of patients with rheumatoid arthritis, as well as psoriatic arthritis." (PMID 40170117, 2025). "Tocilizumab, a humanized monoclonal antibody targeting the IL-6 receptor, inhibits IL-6-driven signaling and is approved for treating rheumatoid arthritis and Castleman’s disease." (PMID 40564167, 2025). "In rheumatoid arthritis, synovial fibroblasts and macrophages produce IL6, contributing to joint destruction, and chronic immune activation further contributes to IL6 overproduction." (PMID 40650062, 2025). "Pan-inhibitors of IL-6 signaling were first developed and approved in several countries for the treatment of chronic inflammatory diseases, such as rheumatoid arthritis, Crohn’s disease, and Castleman disease." (PMID 38980514, 2025). "Patients with rheumatoid arthritis, an autoimmune disease characterized by systemic chronic inflammation, also have elevated levels of circulating IL-6, which promotes sarcopenia." (PMID 40211386, 2025). "Antibodies that block either IL-6 or the IL-6R are in clinical use to treat inflammatory diseases like rheumatoid arthritis, and designer proteins like Olamkicept that target specifically IL-6 trans-signaling are currently investigated in clinical studies." (PMID 40663802, 2025). "IL-6 inhibitors (tocilizumab, sarilumab) are used to treat rheumatoid arthritis, giant cell arteritis, and cytokine release syndrome from CAR-T cell therapy." (PMID 40362303, 2025). "Its mechanism of action involves inhibition of both the classical and trans-signaling pathways of IL-6, and it is mainly used in the treatment of rheumatoid arthritis." (PMID 41256010, 2025). "In this review, we looked at published research on medicines called interleukin-6 (IL-6) inhibitors, already used to treat other conditions such as rheumatoid arthritis." (PMID 39857830, 2025).
rheumatoid arthritis (continued). "A recentstudy has also reported similar interleukin-6 promoter methylation in both rheumatoid arthritis and periodontal disease." (PMID 40636181, 2025). "The reduction in pro-inflammatory cytokines, particularly TNF-α and IL-6, aligns with the known role of these mediators in driving synovial inflammation and joint destruction in rheumatoid arthritis." (PMID 40332334, 2025). "Tocilizumab (TCZ) is an FDA approved humanized mAb for rheumatoid arthritis and cytokine release syndrome in humans, functioning as an interleukin-6 (IL-6) inhibitor by blocking the binding site on the IL-6 receptor (IL-6R)." (PMID 40969347, 2025). "IL-6 injection induces heat and mechanical hyperalgesia andits levels are altered in many painful conditions, including postoperative pain,rheumatoid arthritis, and temporomandibular joint disorders, among several others." (PMID 41436117, 2025). "First, a PBPK model with focus on patients with rheumatoid arthritis (RA) was built, a disease where elevated IL-6 levels are well investigated." (PMID 41404110, 2025). "Some therapeutic approaches targeting IL-6 are available, such as tocilizumab (TCZ), the first IL-6-targeted biologic approved for the treatment of various inflammatory diseases (including rheumatoid arthritis and systemic arthritis)." (PMID 40420944, 2025). "IL‐6 is also a pivotal mediator in numerous autoimmune and chronic inflammatory disorders such as rheumatoid arthritis (RA), diabetes, and Crohn's disease." (PMID 40781971, 2025). "The relationship between Il-6 levels and cognitive function has been noted in numerous studies across different health states, spanning from diseases like rheumatoid arthritis, type 2 diabetes, and schizophrenia to healthy populations." (PMID 41155494, 2025). "Singh A.K., Haque M., Madarampalli B., Shi Y., Wildman B.J., BasitA., Khuder S.A., Prasad B., Hassan Q., Ouseph M.M., Ahmed S.Ets-2 propagates IL-6 trans-signaling mediated osteoclast-likechanges in human rheumatoid arthritis synovial fibroblast." (PMID 41536794, 2025). "Structural optimization of these analogs identified key features (e.g., flexible alkyl chains) necessary for efficacy, with lead compounds demonstrating reduced IL-6 secretion in rheumatoid arthritis models and improved CNS repair in EAE." (PMID 41357216, 2025). "IL-6 was reported to be elevated in the serum of inflammatory diseases patients such as rheumatoid arthritis, Castleman’s disease, and Crohn’s disease." (PMID 40332498, 2025). "The overproduction of pro‐inflammatory cytokines TNF‐α, IL‐1β, and IL‐6 was observed in concanavalin A‐activated peripheral blood mononuclear cells and macrophages extracted from patients with rheumatoid arthritis induced by ENO1." (PMID 40586619, 2025). "Monoclonal antibodies that block IL-6 signaling, such as anti-IL-6 R agents (e.g., tocilizumab), have already demonstrated efficacy in systemic inflammatory disorders, including rheumatoid arthritis and juvenile idiopathic arthritis." (PMID 41007333, 2025). "Increased IL-6 levels are correlated with the severity of disorders such as rheumatoid arthritis and autoimmune encephalitis, making IL-6 a crucial focus in these conditions." (PMID 39755644, 2025). "By inhibiting the release of pro-inflammatory cytokines, such as TNF-α and IL-6, it emerges as a promising therapeutic agent for chronic inflammatory disorders, including rheumatoid arthritis and inflammatory bowel disease." (PMID 40076409, 2025). "IL-6 inhibitors play a crucial role in the treatment of rheumatoid arthritis by reducing inflammation-induced osteoporosis through the suppression of osteoclast activity." (PMID 40873591, 2025). "Atypical CD62L- naïve CD4 T cells have been described in rheumatoid arthritis (RA), where they correlate with disease flares and exhibit IL-1/IL-6/TNF-driven inflammatory signatures." (PMID 40661940, 2025).
rheumatoid arthritis (continued). "IL-6 is also pivotal in the pathogenesis of rheumatoid arthritis and correlates with the disease severity and joint destruction." (PMID 40392222, 2025). "Propolis effectively modulates inflammatory pathways, including NF-κB, reducing cytokines such as TNF-α and IL-6, thus demonstrating efficacy in managing chronic inflammatory conditions like atherosclerosis and rheumatoid arthritis." (PMID 40906303, 2025). "IL-6 has been shown to promote bone formation, but it is also shown to drive osteoclast differentiation and joint degradation in rheumatoid arthritis." (PMID 41185633, 2025). "It has been shown that IL-6 recruited neutrophils in an in vitro co-culture rheumatoid arthritis model." (PMID 40392222, 2025). "A number of approaches are being developed to target the IL-6/JAK/STAT3 pathway some of which have been approved for use in inflammatory diseases such as rheumatoid arthritis." (PMID 40597443, 2025). "Recent findings from East Asian populations have also identified associations between KTCN and pathways related to rheumatoid arthritis, highlighting the activation of immune cells and the release of inflammatory cytokines such as TNF-α, IL-1, and IL-6." (PMID 40426861, 2025). "Mechanistically, IL-17 acts on synovial fibroblasts and stromal cells, induces RANKL and matrix metalloproteinases, and cooperates with TNF and IL-6, which accelerates bone erosion and cartilage damage in rheumatoid arthritis." (PMID 41303386, 2025). "It has already been shown that the addition of tocilizumab, a monoclonal antibody against IL-6, to the treatment of rheumatoid arthritis significantly increases bone density in patients with osteoporosis." (PMID 39940700, 2025). "A 2023 study found that rheumatoid arthritis patients with high IL-6 levels responded better to IFN-γ-primed MSCs, offering a biomarker-driven approach to preconditioning." (PMID 40809065, 2025). "A correlation between IL-6 and MMPs expression has been reported in the context of rheumatoid arthritis." (PMID 40392222, 2025). "The negative consequences of excessive inflammation are highlighted by the fact that cytokine storm syndromes and rheumatoid arthritis are characterized by an overproduction of IL-6." (PMID 39996755, 2025). "The sustained inhibitory effects of PTD on key inflammatory markers (NO, TNF-α, and IL-6) underscore its therapeutic potential in managing chronic inflammatory conditions like rheumatoid arthritis." (PMID 40332334, 2025). "Rheumatoid arthritis leads to the abundant presence of inflammatory factors such as interleukin(IL)-1,IL-6 and tumor necrosis factor (TNF) in the systemic circulation." (PMID 40496851, 2025). "IL‐6 has also been identified to play an important role in the inflammatory pathway of rheumatoid arthritis in humans and has led to the development of targeted anti‐IL‐6 therapy." (PMID 39995340, 2025). "Affecting the Th17/Treg balance, IL-6 takes part in the pathogenesis of chronic autoimmune and inflammatory disorders such as autoimmune hemolytic anemia, rheumatoid arthritis, systemic sclerosis, inflammatory bowel disease, and asthma." (PMID 40191199, 2025). "In rheumatoid arthritis and Castelman’s disease, the inhibition of IL-6 significantly contributes to disease control." (PMID 39518029, 2024). "The synovial fluid and sera of patients suffering from osteoarthritis and rheumatoid arthritis also have higher concentrations of IL-6 and sIL-6R." (PMID 39204123, 2024). "Targeting Th17 cytokines such as IL-6, IL-17, and IL-23 is an effective strategy in rheumatoid arthritis, psoriasis, psoriatic arthritis, and inflammatory bowel disease (IBD)." (PMID 39403935, 2024). "In a recent meta-analysis of HBsAg−/anti-HBc+ patients with rheumatoid arthritis receiving IL-6 inhibitor therapy, the pooled reactivation rate was found to be 0.0% (4 studies; 1 reactivation in 162 patients; I2, 0%; P, 0.43)." (PMID 38257778, 2024).